PTGS2 (prostaglandin-endoperoxide synthase 2)
Diseases named in the same sentence as PTGS2 in open-access papers (continued):
Sharing a sentence is not in itself a finding about the gene and the disease.
psoriasis (13 papers, 2010 to 2025). An autoimmune condition characterized by red, well-delineated plaques with silvery scales that are usually on the extensor surfaces and scalp. "Examples include PTGS2 in psoriasis; PTPN22 in RA and GZMK in IBD." (PMID 20444268, 2010). "Myr was predicted to interact with TNF, PTGS2, and MMP9—targets well documented to contribute to lesion persistence, extracellular matrix remodeling, and inflammatory amplification in psoriasis." (PMID 41471291, 2025). "Multiple inflammatory mediators and signaling pathways contribute to the pathophysiology of psoriasis, including tumor necrosis factor (TNF), prostaglandin–endoperoxide synthase 2 (PTGS2), and interleukin-17A (IL-17A)." (PMID 41471291, 2025). "Their results showed that some specific molecules of ferroptosis (PTGS2, 4-HNE, and ACSl4) enhanced the inflammatory response of psoriasis." (PMID 36276287, 2022). "For instance, several pro‐inflammatory cytokines and arachidonic acid metabolic pathways described to be critical in psoriasis, such as IL‐23, IL‐1α, TNF‐α, TSLP, or PTGS2, were up‐regulated." (PMID 31556482, 2019). "Gene interaction analyses highlighted IFNG, IL4, IL10, MMP9 and TIMP1 in IBD; IL10, IL13 and PTGS2 in psoriasis; IL8, IL10 and PTGS2 in RA." (PMID 20444268, 2010). "The Degree algorithm in CytoScape software was then used to rank the importance of these common genes, and the results showed that genes such as PTGS2 (COX-2) and CXCL8 played the role of core target genes in the process of ergothioneine in alleviating psoriasis." (PMID 40046751, 2025). "Similarly, the upregulation of PTGS2 and TFRC expression and decreased FTL, GPX4, and FTH1 mRNA levels were observed in psoriasis samples." (PMID 39308857, 2024). "Regarding the candidate targets, estrogen receptor (ESR1) showed the highest degree (113°), followed by PTGS2 (86°), NOS2 (81°), PPARG (60°), and GSK3B (56°), which demonstrated the potential therapeutic effect of each drug in LXJD formula for ameliorating psoriasis." (PMID 34168554, 2021). "Among all the targets, the top three were PTGS2, MAPK14, and NOS3 in terms of Degree, and all of them have been demonstrated to play important roles in the pathogenesis of psoriasis, such as inflammatory infiltration, abnormal differentiation of keratinocytes, and oxidative stress injury." (PMID 32655662, 2020).
ischemia (12 papers, 2005 to 2025). A hypoperfusion of the BLOOD through an organ or tissue caused by a PATHOLOGIC CONSTRICTION or obstruction of its BLOOD VESSELS, or an absence of BLOOD CIRCULATION. "Consistent with a known contribution of ferroptosis in IRI, mRNA levels of Ptgs2 were much higher in ischemia group, which was prevented in CH diet fed mice." (PMID 37914914, 2023).
Nephropathy (12 papers, 2013 to 2025). A nonspecific term referring to disease or damage of the kidneys. "Consequently, targeted adjustment of PTGS2 could be a viable approach for treating renal diseases." (PMID 38332893, 2024). "It is reported that PTGS2 (also known as COX-2) was involved in podocyte injury and various renal pathological processes such as renal interstitial fibrosis, showing a potential therapeutic target against lupus nephritis-induced nephropathy." (PMID 32025234, 2020).
pulmonary hypertension (12 papers, 2011 to 2025). Increased pressure within the pulmonary circulation due to lung or heart disorder. "First, the mechanistic roles of identified hub genes, including VEGFA, MDM2, and PTGS2, must be functionally assessed using both in vitro and in vivo pulmonary hypertension models." (PMID 41137320, 2025).
Hepatic steatosis (11 papers, 2017 to 2025). Steatosis is a term used to denote lipid accumulation within hepatocytes. "The administration of ECH resulted in a reduction in hepatic PTGS2 expression, hepatic steatosis, lipid droplet deposition and the number of dead hepatocytes in MASLD mice." (PMID 39767635, 2024). "The inhibitor of PTGS2 could significantly alleviate hepatic steatosis by regulating lipid synthesis." (PMID 35126150, 2021). "Selective PTGS2 inhibitors could significantly ameliorate hepatic steatosis, inflammation, and liver injury in NASH models." (PMID 35126150, 2021). "When PTGS2/COX-2 signaling is activated during inflammation in adipose tissue, it can act as a crucial factor for the promotion of obesity-induced IR and fatty liver." (PMID 35740337, 2022). "Furthermore, limonin can reduce hepatic steatosis, lipid accumulation, and the expression of p-STAT3/STAT3, caspase-8, and prostaglandin-endoperoxide synthase 2, and improve the inflammatory response of non-alcoholic fatty liver." (PMID 39944619, 2025).
inflammatory bowel disease (11 papers, 2007 to 2026). A spectrum of small and large bowel inflammatory diseases of unknown etiology. "For example, we found that PTGS2, an important target of Turkish galls, was associated with inflammation-associated diseases, such as inflammatory bowel disease, in the T-D network." (PMID 28446747, 2017).
influenza (11 papers, 2013 to 2026). An acute viral infection of the respiratory tract, occurring in isolated cases, in epidemics, or in pandemics; it is caused by serologically different strains of viruses (influenzaviruses) designated A, B, and C, has a 3-day incubation period, and usually lasts for 3 to 10 days. "While PTGS2 activity has previously been linked to influenza infection and PM exposure, PTGS2 upregulation was only detected in samples exposed to Spring and Winter PM prior to influenza infection." (PMID 40671793, 2025). "A holistic C-D-T network was generated by merging three networks to determine the factors involved in influenza-associated inflammation, which yielded two main active compounds (BS and PG) and main targets (PTGS1 and PTGS2)." (PMID 32854331, 2020).
lung adenocarcinoma (11 papers, 2014 to 2024). A carcinoma that arises from the lung and is characterized by the presence of malignant glandular epithelial cells. "c-MET and PTGS2 proved highly expressed in several patient lung adenocarcinoma samples, along with several other tumor types in cBioPortal database." (PMID 32545325, 2020). "Subsequently, it is verified that 9 core targets for ginseng treatment of lung adenocarcinoma, namely, JUN, IL-1β, IL-2, ICAM1, HMOX1, MMP9, MMP2, PTGS2, and TNF, are closely related to the proliferation, migration, and apoptosis of lung adenocarcinoma cells." (PMID 32802118, 2020). "Meanwhile, according to the results of qRT-PCR, it is speculated that ginseng can treat lung adenocarcinoma by up-regulated JUN, IL-1β, IL-2, ICAM1, HMOX1, MMP9, and MMP2 targets and down-regulated PTGS2 and TNF genes." (PMID 32802118, 2020).
myocardial ischemia (11 papers, 2015 to 2025). A disorder of cardiac function caused by insufficient blood flow to the muscle tissue of the heart. "Network pharmacology analysis identified NOS3 and PTGS2 as core acute myocardial ischemia targets." (PMID 37234713, 2023).
oral cancer (11 papers, 2015 to 2025). "Confirming and extending our previous results, PTGS2 (cyclooxygenase-2) and several cyclooxygenase-related genes were significantly up-regulated in 4-NQO-induced oral cancers; up-regulation of PTGS2 was associated with promoter hypomethylation." (PMID 25635769, 2015). "Confirming and extending our previous results, PTGS2 and several COX-related genes were significantly upregulated in rat oral cancers induced by 4-NQO; upregulation of PTGS2 is associated with hypomethylation of its proximal promoter region." (PMID 25635769, 2015). "Overexpression of pro-inflammatory chemokines, hypomethylation and overexpression of PTGS2, and hypermethylation and underexpression of APC2 may all be causally linked to the etiology of oral cancer in this model." (PMID 25635769, 2015). "Our methylation analyses demonstrate that PTGS2 is upregulated in oral cancers through an epigenetic mechanism involving hypomethylation of the PTGS2 proximal promoter; interestingly, significant hypomethylation was seen outside of the CpG island region of the promoter." (PMID 25635769, 2015). "Overexpression of pro-inflammatory chemokines, hypomethylation of PTGS2, and hypermethylation of APC2 may be causally linked to the etiology of oral cancer in this model." (PMID 25635769, 2015).
Anxiety (10 papers, 2016 to 2026). Intense feelings of nervousness, tension, or panic often arise in response to interpersonal stresses. "Additional targets have been shown to be associated with anxiety disorders, for example, psilocybin, a drug with therapeutic potential for anxiety, which reduces the expression of prostaglandin-endoperoxide synthase 2 (PTGS2) in the hippocampus." (PMID 35624976, 2022). "Notably, quercetin, luteolin, kaempferol, nobiletin and formononetin have been screened to be crucial for the treatment of adolescent depression combined with anxiety with Si-ni San, which exhibited strong binding affinities to PTGS2." (PMID 39247617, 2024). "However, it remains unknown whether PTGS2 is directly related to anxiety." (PMID 35624976, 2022).
diabetic nephropathy (10 papers, 2008 to 2025). "The disease-associated genes like PI3K-AKT, PPARG and PTGS2 have biological importance in diabetic nephropathy." (PMID 40435181, 2025). "The study found important targets, including TNF, CREB1, and PTGS2, indicating that CR-C1 may be important in lowering oxidative stress and inflammation in diabetic nephropathy." (PMID 40435181, 2025). "Meanwhile, specific knockdown of PTGS2 in podocytes exacerbates diabetic nephropathy." (PMID 36482994, 2022). "The expression of PTGS2 in macrophages prevents the development of diabetic nephropathy." (PMID 36482994, 2022). "In addition to being directly related to T2DM, the polymorphisms of VEGFA, EGFR, PTGS2, and AKT1 genes are mainly related to diabetic vascular dysfunction and play an important role in diabetic vascular disease and diabetic nephropathy." (PMID 33134394, 2020). "Rosmarinic acid has been demonstrated to protect against diabetic nephropathy by inhibiting AGE formation and downregulating the expression of RAGE and PTGS2." (PMID 39458839, 2024).
diabetic retinopathy (10 papers, 2012 to 2026). "The hub genes HMOX1 and PTGS2, and their associated transcription factors and miRNAs, may be involved in ferroptosis in diabetic retinopathy." (PMID 36689408, 2023). "In conclusion, we found that HMOX1 and PTGS2 are hub genes involved in ferroptosis process of diabetic retinopathy." (PMID 36689408, 2023). "In addition, the vascular endothelial growth factor signaling pathway that involving many target proteins, such as INSR, NOS3, PTGS2, and vascular endothelial growth factor A (VEGFA), plays a key regulatory role in diabetic retinopathy." (PMID 32265717, 2020). "Besides, the VEGF signaling pathway played an important role in the diabetic retinopathy involved in multiple targets including PIK3CG, PTGS2, and VEGFA." (PMID 29051733, 2017).
dyslipidemia (10 papers, 2015 to 2023). "Remarkably, in dyslipidemia, there was a reduction in the expression of inflammatory genes (e.g. ATF3, DUSP2 and PTGS2)." (PMID 26083362, 2015).
gastric ulcer (10 papers, 2008 to 2024). An ulcerated lesion in the mucosal surface of the stomach. "The PTGS2 gene was found to be the most represented gene by seven compounds related to gastric ulcer." (PMID 38728332, 2024). "The administration of FL significantly lowered the gastric mRNA expression of inflammation-related genes, including NF-κb1, tumor necrosis factor-α, interferon γ, and prostaglandin-endoperoxide synthase 2, compared with the gastric ulcer control group." (PMID 32204312, 2020). "The pharmacology network explained target genes related to the identified metabolites to possess 672 interactions between the 18 identified metabolites and 379 genes, among which PTGS2, MMP2 and PTGS1 were the top annotated genes related to gastric ulcer." (PMID 38355510, 2024). "The PTGS2, MMP2 and PTGS1 were the top annotated genes related to gastric ulcer." (PMID 38355510, 2024).
migraine (10 papers, 2015 to 2025). "Studies have shown that PTGS2 participates in the pathogenesis of migraines, and the symptoms of migraine patients can be improved by inhibiting the PTGS2 proinflammatory pathway and reducing the levels of TNF-α, IL-2, and IL-6." (PMID 41009787, 2025). "In Chinese traditional medicine, WZY is a traditional drug for migraines, possibly relating to alkaloids’ strong affinity to PTGS2, which corresponds with our finding—four compounds contained in WZY showed great value in treating migraines." (PMID 37570816, 2023). "PTGS2, PTGS1, PPARG, ADRB2, GABRA1, and NOS3 are potential targets for the treatment of migraines using ginkgo seeds due to their advantageous values." (PMID 41009787, 2025). "Moreover, molecular docking results demonstrated that these core components have a strong affinity with multiple target proteins such as PTGS2, PPARG, BCL2, CASP3, TNF, and ESR1, suggesting that ginkgo seeds exert their therapeutic effects on migraines through multiple targets and pathways." (PMID 41009787, 2025). "Such active ingredients may influence neuroactive ligand-receptor interaction, calcium signaling pathways, signaling pathways in cancer, cAMP signaling pathways, and PI3K pathways by acting on multiple targets such as PTGS2, PIK3CA, PIK3CB, PIK3CD, F2, and AR to treat migraine." (PMID 36479181, 2022). "Also, we identified a great number of direct connections between PTGS2 and different drugs, such as tolfenamic acid, a nonsteroidal anti-inflammatory drug (NSAID) usually used for migraine pain." (PMID 34668739, 2021).
squamous cell carcinoma (10 papers, 2002 to 2025). A carcinoma arising from squamous epithelial cells. "In contrast, other investigators have suggested that c-Jun interacts with the CRE of the prostaglandin endoperoxide synthase-2 promoter in epidermal growth factor-treated human epidermoid carcinoma cells." (PMID 40871473, 2025). "In support to this proposal, it should be noted that high PTGS2 expression was found in actinic keratoses, the pre-neoplastic lesions precursor of squamous cell carcinoma." (PMID 39560493, 2024).
ulcers (10 papers, 2009 to 2025). "PTGS2 plays the most important role in the treatment of mucosal defense and gastrointestinal inflammation and ulcers." (PMID 35631773, 2022).
cystitis (9 papers, 2012 to 2025). Inflammation of the urinary bladder. "We also specifically analyzed the gene expression pattern of TNFɑ, along with cyclooxygenase-2 (COX-2, encoded by the Ptgs2 gene), an enzyme critical in mediating urothelial inflammation during severe acute and recurrent cystitis." (PMID 31429405, 2019). "Hispidulin also can suppress the expressions of PTGS2 and NLRP3 inflammasome to improve cyclophosphamide-induced cystitis." (PMID 41340657, 2025). "Furthermore, hispidulin can ameliorate cyclophosphamide-induced cystitis by suppressing NLRP3 inflammasome activation, achieved through targeting prostaglandin G/H synthase 2 (PTGS2)." (PMID 40832584, 2025). "We found that the kinetics of TNFɑ expression and pathway activation mirrored the kinetics of Ptgs2 (COX-2) expression regardless of disease history, suggesting that TNFɑ signaling may be associated with Ptgs2 expression during bladder infection." (PMID 31429405, 2019).
head and neck cancer (9 papers, 2013 to 2025). A primary or metastatic malignant neoplasm affecting the head and neck. "In silico analysis performed in TCGA, PanCancer Atlas for head and neck cancers, demonstrated significant expression and co‐expression of PTGS2 and genes that regulate VEGF signalling." (PMID 38426619, 2024). "Through HPA database, we also found that PTGS2 and MMP3 are expressed in various cancers, including head and neck cancers." (PMID 36555343, 2022). "Our data have also shown increased mRNA level of pro-inflammatory cytokines such as Il1a, Il1b, Tnf, Ptgs2 in mouse ASCC as compared with control anal skin, which is well demonstrated in human and mice head and neck cancer." (PMID 24124460, 2013). "We also performed correlation analysis based on TCGA data from colon and head and neck carcinoma provided in UCSC Xena which confirmed that CA9 and PTGS2 expression does not correlate (correlation coefficient -0.004 and 0.04 for COAD and HNSC, respectively)." (PMID 40408503, 2025).
leukemia (9 papers, 2013 to 2025). A malignant (clonal) hematologic disorder, involving hematopoietic stem cells and characterized by the presence of primitive or atypical myeloid or lymphoid cells in the bone marrow and the blood. "There are several reports on the in vitro effects of NSAIDs and the expression of PTGS1 and PTGS2 in leukaemia cell lines." (PMID 40444088, 2025). "Such Benzene network functions are associated with leukemia mechanisms, and several of these functions and processes are mediated by IL1A and PTGS2, which play a central role in the characterization of gene expression associated with benzene exposure." (PMID 37298367, 2023). "We found that CXCL1, CXCL6, TEP1, IL8, CCL2 and PTGS2 genes were the most up-regulated genes in BMSCs co-cultured in the direct contact with leukemia cells." (PMID 24304929, 2013). "It was reported that inhibition of PTGS2 (also named COX2) correlates with the decreased expression of NR4A transcription factors and Treg genes in leukemia." (PMID 33373316, 2020).
renal failure (9 papers, 2005 to 2024). "On one hand, excessive PTGS2 expression exacerbates the inflammatory response, causing harm to the kidneys, while on the other hand, excessive suppression of PTGS2 may elevate the risk of hyperkalemia and renal failure." (PMID 38332893, 2024). "The only definite conclusion drawn is that PTGS2 may heighten the risk of acute renal failure when RAAS inhibitors are active in DN conditions." (PMID 38332893, 2024). "Among the targets of RAAS inhibitors, PTGS2, ITGA4 and ANPEP have a causal relationship with acute kidney injury, which is worthy of further clinical research." (PMID 38332893, 2024).
ulcerative colitis (9 papers, 2017 to 2025). An inflammatory bowel disease involving the mucosal surface of the large intestine and rectum. "Ptgs2 can repair the injured intestinal mucosa and exert a critical role in the pathophysiology of Salmonella typhimurium-induced ulcerative colitis." (PMID 31341536, 2019). "The findings indicated that FS could modulate the progression of ulcerative colitis via multiple targets, with STAT3, EGFR, ESR1, PTGS2, NF-κB1 and JUN identified as the six key targets significantly involved in the pathogenesis and progression of ulcerative colitis." (PMID 40649400, 2025).
acne (8 papers, 2021 to 2025). An inflammatory process of the sebaceous glands which is characterized by comedones, nodules, papules and/or pustules on the skin. "Previous studies showed that important inflammatory molecules, such as IL6, IL8, TNFα, 5-lipoxygenase (5LOX) or cyclooxygenase 2 [COX2; a.k.a. prostaglandin-endoperoxide synthase (PTGS2)] are increased in lesional sebocytes of acne patients." (PMID 36439142, 2022). "Using a murine/human aGVHD gene signature we identified a cluster of ITGAX+CD14+S100A9+PTGS2+ macrophages that expanded in psoriatic but not acne skin compared with healthy controls." (PMID 35584681, 2022). "Moreover, the prominent induction of genes, such as PTGS2, CXCL8, IL6, IL1B, matrix metalloproteinase 1 (MMP1) and NLRP3, even raised the possibility that EGF and PA may be involved in the pathogenesis of acne." (PMID 34025636, 2021).